ILK (integrin linked kinase)
Diseases named in the same sentence as ILK in open-access papers (continued):
Sharing a sentence is not in itself a finding about the gene and the disease.
cancer (continued). "Therefore, ILK should be evaluated as a potential anti-cancer pharmaceutical target." (PMID 33043811, 2020). "PI3Ks activity can lead to cancer cell migration, adhesion, and malignant transformation, together with degradation of the extracellular matrix, which prohibit autophagy and enhance EMT by up-regulating SNAIL, SLUG, integrin-linked kinase (ILK), and WNT/β-catenin signaling." (PMID 31126310, 2019). "However, it is unknown whether there is also an interaction between ILK and RI in cancer progression and the mutual relationship has remained unclear so far." (PMID 27576342, 2016). "Moreover, the effectiveness of oral T315 to disrupt this regulatory loop and reverse mesenchymal phenotype in vivo provides a proof-of-concept that inhibition of ILK by small-molecule agents represents a therapeutically relevant strategy to reduce the aggressive phenotype of cancer cells." (PMID 25821081, 2015). "This regulatory feedback loop underlies the ability of cancer cells to maintain high HIF-1α expression in hypoxic conditions, and also explains the high endogenous levels of HIF-1α observed in PC-3 and DU-145 cells, both of which exhibit upregulated ILK expression." (PMID 25821081, 2015). "Therefore, increased multinucleation observed when ILK is downregulated may be a unique anticancer mechanism ultimately leading to the gradual elimination of multinucleated cancer cells and to tumour regression." (PMID 24911651, 2014). "This in silico result was validated by our in vitro co-culture model, demonstrating that fibroblasts regulate ILK and FAK signaling in cancer cells." (PMID 41405822, 2025). "The ILK inhibitor, QLT-0267, is a promising chemotherapeutic drug as it targets clustered, supernumerary centrosomes found in cancer cells." (PMID 37508338, 2023). "Combination therapies targeting ILK and ABL’s oncogenic counterpart BCR-ABL are preferred for other cancers like leukemia when anti-ABL monotherapies are ineffective." (PMID 37508338, 2023). "ILK and ABL have both been studied individually for their role in cancer cell division and survival." (PMID 37508338, 2023). "Taken together, the results suggest that ILK expression is correlated with the infiltration of CAFs and their markers and EMT markers in different cancers." (PMID 35692780, 2022). "Several upregulated genes (LRP1, SERPINA1, HRG, ILK, CAV1, and LAMA4) identified in our study are involved in GEM resistance in human cancer 23-28." (PMID 35281857, 2022). "In contrast, suppression of ILK reduces EMT markers and inhibits invasion and metastasis in many cancer types." (PMID 35804980, 2022). "While the intricacies of ILK signaling in AML require further investigation, its role both in cell survival and immune invasion highlights its potential as a cancer-specific target in this context." (PMID 35804980, 2022). "The results showed that ILK expression is significantly higher in primary tumors and their adjacent non-tumor tissues from CRC patients compared with individual’s non-cancer tissues." (PMID 35692780, 2022). "We found that aberrant expression of truncated O-glycans in SC cells tremendously upregulates the phosphorylation of ILK/FAK and exacerbates cancer progression." (PMID 35628269, 2022). "It is now well-recognized that ILK and ILK-mediated signaling is centrally involved in the process of EMT by cancer cells." (PMID 35804980, 2022). "Altogether, these data suggest that stimulation of cancer cells to develop invadopodia by plating on ECM occurs through the formation of a protein–protein complex formed by β1-integrin, ILK, p(T567)-ezrin, NHERF1 and NHE1." (PMID 33671549, 2021). "However, in the cancer context, it is suggested that ILK may display an opposite function." (PMID 34163519, 2021). "However, it has not been investigated whether ILK is directly linked to senescent cancer cells or not." (PMID 34163519, 2021).
cancer (continued). "Nonetheless, there is less understanding about the role of ILK in senescence and its inflammatory response or SIR in a cancer context." (PMID 34163519, 2021). "ILK/AKT/mTOR signaling pathway is widely known for modulating cell growth, differentiation, apoptosis, cellular metabolism and cancer cell survival." (PMID 27576342, 2016). "Thus, PARVA might contribute to cancer progression by activating ILK." (PMID 25738875, 2015). "Both the knockdown of ILK expression and inhibition of ILK activity markedly decreased the PARVA-induced invasive capacity of the cancer cells." (PMID 25738875, 2015). "In summary, we obtained evidence that the HIF-1α-ILK regulatory loop plays a critical role in maintaining HIF-1α expression and regulating EMT in cancer cells via multiple mechanisms in a cell line- and cellular context-specific manner." (PMID 25821081, 2015). "ILK has been shown to play an important role in cell proliferation in tissue culture and PINCH is frequently upregulated in human cancers." (PMID 22879977, 2012). "We postulate that the differential therapeutic effect of ILKI in MDA‐MB‐231 and MCF‐7 3D tumoroid models with distinct stromal compositions can be explained by the interplay between stromal cell and cancer cell type, ECM remodeling, and ILK‐driven signaling pathways." (PMID 41537745, 2026). "Similarly, 313 regulated phosphosites indicated a major impact on actin, as well as ‘ILK signaling’, ‘FAK signaling’, and ‘Molecular mechanisms of cancer’ among the most altered pathways." (PMID 40052672, 2025). "It was also found that the ILK/Rictor complex forms in cancer cells but not in normal cells, making it a promising target for cancer-specific therapy that is not harmful to normal cells." (PMID 38339294, 2024). "al found that, the transmembrane protein coiled-coil domain containing 25 (CCDC25) functions as a receptor for NETs-DNA on the surface of cancer cells, activating the ILK/β-parvin/RAC1 pathway and enhancing cancer cell motility by sensing extracellular NETs-DNA." (PMID 38664728, 2024). "The integrin/ILK/NF-κB, IGF1R/PI3K/AKT, and Wnt/β-catenin pathways, as well as certain micro-RNAs have been proven to regulate or be regulated by IGFBP2 in a variety of malignant tumors." (PMID 39221034, 2024). "Individually, ILK and ABL are promising targets for many cancers." (PMID 37508338, 2023). "During the outgrowth of disseminated cancer cells in different organs, including the brain, the YAP activation was induced by L1CAM-dependent cancer cell spreading on the vasculature, through activation of β1 integrin and ILK." (PMID 37456245, 2023). "Apart from structural remodeling of the ECM scaffold, the cell mechanical cues on the ECM network are important players in the malignant progression of cancers, including elevated motility via the IPP complex created by focal adhesion adaptor proteins, such as PINCH1, ILK-1 and Parvin." (PMID 37287457, 2023). "Here, we show a correlation of ILK expression with the immunosuppressive TME and cancer prognosis." (PMID 35692780, 2022). "ILK expression also showed a negative correlation with tumor purity indicating that it is highly expressed in TME possibly by different non-cancer cells." (PMID 35692780, 2022). "We found similarities in pathways and upstream regulators of FOXO3-deficient macrophages with HFD obese mice colon associated with inflammation (IL-1A, IL-1B, IL-6, IL-8 signaling), growth (ILK signaling, CDK5 signaling, VEGF signaling) and cancer (cAMP-mediated signaling)." (PMID 35323693, 2022). "Notably, an ILK inhibitor disrupts the α-Catulin-KLF5 interaction, promotes the degradation of KLF5, and decreases α-Catulin-driven cancer stemness." (PMID 35154481, 2022). "The results overall show that ILK has significant negative correlations with tumor purity in 12 cancers." (PMID 35692780, 2022).
cancer (continued). "ILK signaling also regulates the Hippo tumor suppressor pathway, since ILK-mediated phosphorylation of MYPT-1 results in negative regulation of the Hippo pathway, which has effects on cancer cell growth, invasion, and drug resistance pathways." (PMID 35804980, 2022). "Furthermore, ILK was significantly correlated with B cells and CD8+ T cells in 10 cancers, with CD4+ T cells in 24 cancers, with macrophages and neutrophils in 23 cancers, and with DCs in 28 cancers." (PMID 35692780, 2022). "Therefore, ILK interacts directly or indirectly with different proteins to regulate stemness and EMT, implicating a role for ILK in cancer progression and metastasis." (PMID 34163519, 2021). "The involvement of the α5β1 integrin-ILK axis was ruled out on the cancer cell side owing to the eventual changes of other adhesion-associated molecules." (PMID 33921783, 2021). "This inhibitor was very drastic in deactivating ILK, which led to MDA-MB-231 cancer cell apoptosis." (PMID 33043811, 2020). "Ingenuity Pathway Analysis of the PROM1+ cell transcriptome, also revealed significantly regulated stemness and tumorigenesis pathways such as pluripotency, EMT, tissue factor in cancer, Ephrin receptor, HIPPO pathway, and ILK signaling, suggesting their potential involvement in liver tumorigenesis." (PMID 33173221, 2020). "Regarding signaling pathways modulating cancer cell invasion, the reduction of A2780 cell motility was observed upon the blockade of Smad 2/3 and ILK but not AP-1." (PMID 30609691, 2019). "More precise mechanisms as to how cancer cells reconnect mitochondrial dynamics to the invasion machinery, including how RhoT-TRAK interaction is regulated by ILK at FAs, also warrant additional investigation, although these issues are far beyond the scope of our present study." (PMID 29992963, 2018). "The expression and activity of ILK are elevated in a variety of cancers but its mechanisms are not exactly understood." (PMID 27683053, 2016). "To ensure that the exogenous expression of the different proteins (e.g., FAK, ILK, etc.)did not contribute to FA stability, we expressed them in U2-OS human carcinoma cells without coexpressing active forms of vinculin and under tension-releasing drugs." (PMID 23375895, 2013). "Although it is understood that ILK is an important therapeutic target in cancer, the data summarized here and elsewhere suggest that an ILK inhibitor such as 267 given alone will not achieve much more than a delay in tumor progression." (PMID 19409087, 2009). "Therefore, the effect of an ILK inhibitor is less prominent because it is not targeting a key, stiffness‐induced dependency of cancer cells." (PMID 41537745, 2026). "The role of ABL in cancer centrosomes has not been studied and the effects of drugs that target ILK and ABL at cancer centrosomes is unknown." (PMID 37508338, 2023). "Thus, ILK and ABL inhibitors together, may work in a complementary manner to inhibit centrosome function in cancer cells." (PMID 37508338, 2023). "However, in cancer context, this has not been investigated but our results indicate a possible function for ILK in macrophage polarization and infiltration in TME." (PMID 35692780, 2022). "In contrast, ILK expression in KIRC is not negatively correlated with tumor purity and showed weaker associations with immune cell infiltration compared with the other 3 cancer types." (PMID 35692780, 2022). "It is suggested that the overall contribution of ILK to the TME or cancer cells may depend on the presence or absence of specific type of immune cells or CAFs but this remains to be resolved." (PMID 35692780, 2022). "In order to confirm the upregulation of ILK in adjacent non-tumor tissues and to determine the overall ILK expression level in cancer tissues, we examined the differential expression of ILK in colon tissues from CRC patients and non-cancer individuals in the dataset GSE95132 downloaded from GEO." (PMID 35692780, 2022).
cancer (continued). "A microRNA, MiR-542-3p, is downregulated in human CRC cancers and introducing this microRNA into HCT116 and SW620 CRC cells changes the morphology of the cells and reduces cell adhesion, as well as suppressing invasion via downregulation of the ILK/FAK/c-Src pathway." (PMID 34163519, 2021). "Analysis of Matrigel proteolysis revealed that both breast and prostate cancer cell lines responded similarly to β1-integrin activation (P4G11 antibody) or inhibition (P5D2 antibody) alone and in combination with the inhibition of ILK (Cpd22, 5 μM) or NHE1 (cariporide, 5 μM)." (PMID 33671549, 2021). "In contrast, ILK may regulate STAT3 indirectly via its dependent pathway, PI3K/Akt, in cancer." (PMID 34163519, 2021). "A small number of hypoxia-associated genes (APLN, HIF1A, and BNIP3), cancer stem cell (CSC) markers (CD24 and CD44), hormonal regulation (HR) genes (ESR1, PGR, and TFF1), other selected genes (PPARGC1A, ILK), and HKGs (RPL32, GUSB, TBP, OAZ1 and NONO) were also included in the panel." (PMID 34206049, 2021). "ILK may thus upregulate COX-2 and MIG-7 to enhance EMT and migration/invasion of cancer cells." (PMID 25004182, 2014). "Indeed, the dose (at nM level) used in our study was much lower than that in previous studies, in line with the notion of the preferential dependency of ILK functions in cancer cell survival regardless of adhesion-dependent or independent manner than integrin-mediated cell attachment." (PMID 35778385, 2022). "Finally, we show that the small-molecule ILK inhibitor T315 can disrupt this regulatory loop in vivo and suppress xenograft tumor growth, thereby providing proof-of-concept that targeting ILK represents an effective strategy to block HIF-1α expression and aggressive phenotype in cancer cells." (PMID 25821081, 2015). "Unlike ILK, ABL’s role in mitotic “cancer” centrosomes is not well understood and most studies have focused on the ABL fusion gene product (BCR-ABL)." (PMID 37508338, 2023). "In contrast, 6 datasets that display lower ILK mRNA expression in CRC compared with normal tissue and used adjacent non-tumor tissues from cancer patients." (PMID 35692780, 2022). "We found that ILK, immune and CAF gene markers overall are upregulated in the primary tumors and their adjacent non-tumor tissues compared with non- cancer tissues." (PMID 35692780, 2022). "Moreover, ILK and TKI used in combination show strong synergistic effects on cancer cells while having no adverse effects on normal bone marrow cells." (PMID 37508338, 2023). "This suggests that the ILK negative correlation with tumor purity as well as ILK positive correlation with CAFs and immune cell infiltration is due to higher ILK expression in the TME non-cancer cells." (PMID 35692780, 2022). "On the other hand, Snail1 is controlled at the transcriptional level by various molecules, including ILK, and one cannot rule out that despite its involvement in EMT of cancer cells, the induction of MMT in PMCs acts through ILK and Snail1 mRNA but bypasses Snail1 protein." (PMID 31086083, 2019).
tumor (201 papers, 2003 to 2026). "The developed 3D tumoroids enabled investigating the efficacy of an integrin linked kinase inhibitor and comparing its effect on the tumor mass and the stromal compartment." (PMID 41537745, 2026). "ILK, an integrin-linked kinase, regulates integrin signaling and is associated with tumor growth and metastasis." (PMID 39723668, 2025). "ILK intensity (p = 0.032) and positive PD-L1 (p = 0.034) were associated with more advanced tumor stages." (PMID 39685780, 2024). "FAK and ILK, known to be overexpressed in EC, are strongly linked to tumor cell survival, proliferation, invasion, and migration." (PMID 38727811, 2024). "Our study demonstrates the ratios of CD8/FOXP3 correlate with the tumour burdens in both AOM/DSS and APCmin/+ models, indicating an impact of myeloid-ILK deficiency on the differential tumour-infiltration of T cells." (PMID 38077324, 2023). "Myeloid-ILK deficiency also enhances tumour-infiltration of CD8+ T cells and reduces FOXP3+ T cells in CAC and APCmin/+-driven CRC, respectively, with a significantly elevated CD8+/FOXP3+ ratio indicating a tumoricidal impact in both models." (PMID 38077324, 2023). "In contrast, reactive stroma close to tumour foci was characterised by oxidative stress and integrin-linked kinase (ILK) signalling." (PMID 36482187, 2023). "Similar to the AOM/DSS model, the proportion of APCmin/+ -driven tumours that progressed to high-grade adenocarcinomas was reduced in myeloid-ILK deficient APCmin/+ mice compared to the WT control." (PMID 38077324, 2023). "In contrast, for the APCmin/+ model, the tumour infiltration of FOXP3+ T cells were reduced by myeloid-ILK deficiency whereas the infiltration of CD8+ T cells remained unaffected." (PMID 38077324, 2023). "As a result, it enhanced tumor cell motility and tumor metastasis by activating the downstream pathway including integrin-linked kinase (ILK) and β-Parvin." (PMID 36859358, 2023). "Accordingly, to examine the effect of myeloid-ILK deficiency on the tumour-infiltration of T cells, the tumour-infiltrated regulatory FOXP3+ and cytotoxic CD8+ T cells in both models of CRC were quantified." (PMID 38077324, 2023). "Collectively, these results demonstrate marked tumour suppression by myeloid-ILK deficiency in both carcinogen/inflammation and oncogene-driven models of colon tumorigenesis." (PMID 38077324, 2023). "In both models, the ratio of CD8+/FOXP3+ T cells in tumours were significantly elevated in myeloid-ILK deficient mice compared the ILK-sufficient controls." (PMID 38077324, 2023). "One of the most explored and reviewed topics associated with ILK covers a widely studied role in tumor development, prevention, and treatment." (PMID 35089438, 2022). "Integrin-linked kinase (ILK) is a serine-threonine protein kinase in the lysates of animal epithelial cells and tumor cells." (PMID 35571621, 2022). "We found that MUC16 enhances tumor malignancy by activating the integrin-linked kinase and focal adhesion kinase (ILK/FAK)-signaling axis." (PMID 35628269, 2022). "The past decade has seen dramatic advances in our understanding of the importance of ILK as a signaling effector in several processes linked to tumor progression and metastasis." (PMID 35804980, 2022). "Here, we discuss recent advances in our understanding of the importance of ILK as a signaling effector in processes linked to tumor progression and metastasis." (PMID 35804980, 2022). "Integrin-linked kinase (ILK) was discovered more than two decades ago and was subsequently validated as a promising target for neoplastic diseases." (PMID 35869378, 2022). "ILK is closely related to tumor grade and survival and its up-regulation is associated with poor prognosis." (PMID 35676936, 2022). "Consistent with our in vitro data, the growth of xenografic tumor bearing ILK deficient MKN1 cells was significantly reduced in immune-compromised NOD-SCID-gamma (NSG) mice." (PMID 35778385, 2022).